CHD5 (chromodomain helicase DNA binding protein 5)
Diseases named in the same sentence as CHD5 in open-access papers (continued):
Sharing a sentence is not in itself a finding about the gene and the disease.
tumor (continued). "Their analysis of different candidate 1p36 tumor suppressor genes, such as Arid1a, Chd5, Camta1, and Kif1b, identified Arid1a as the gene with strongest correlation between expression levels and time to tumor onset." (PMID 34885007, 2021). "It was found that the average tumor weight and average tumor volume of the CHD5-OE group were significantly lower than those of the Ctrl-OE and NC groups." (PMID 33062682, 2020). "Chromodomain helicase DNA-binding protein 5 (CHD5) plays a crucial tumor suppressor role in multiple types of tumors." (PMID 33062682, 2020). "Overexpression of CHD5 inhibited proliferation, migration, and invasion in vitro; prompted cell cycle G1 phase arrest; induced apoptosis; and suppressed tumor growth in vivo." (PMID 33062682, 2020). "The results showed that the expression of CHD5 was obviously downregulated in tumor tissues compared to matched adjacent tissues." (PMID 33062682, 2020). "CHD5 is a tumour-suppressing gene of the chromodomain gene family, first identified as a tumour-suppressing gene mapping to 1p36.31." (PMID 29907144, 2018). "Of these, CHD5 is a potential tumor suppressor regulating the expression of genes involved in cell proliferation and differentiation." (PMID 30485296, 2018). "In contrast to CHD3 and CHD5, which most likely function as tumor suppressors, the role of CHD4 in various tumors appears to be quite complex." (PMID 28055972, 2017). "In 7978 sequenced TCGA tumor samples, four CHD genes—CHD4, CHD5, CHD6, and CHD7—exhibited mutations in more than 200 tumor samples." (PMID 28649742, 2017). "The dual PHDs of Chd5 specifically interacts with unmodified N-terminus of histone H3, which is ciritical for Chd5 to exert the regulatory role on gene expression and the potential tumor suppressive function." (PMID 26943038, 2016). "In this study, we demonstrated that CHD5 acted as a functional tumor suppressor and was frequently silenced by promoter CpG methylation in RCC." (PMID 26943038, 2016). "We further investigated the possible mechanism of CHD5 functioning as a tumor suppressor in RCC cells." (PMID 26943038, 2016). "CHD5 is located at 1p36, together with other tumor suppressors including p73, CAMTA1, miR-34a, KIF1β, and CASZ1." (PMID 26943038, 2016). "Here, we further studied the epigenetic alteration of CHD5 in RCC cells, and characterized its tumor suppressive functions and the underlying molecular mechanisms during RCC pathogenesis." (PMID 26943038, 2016). "CHD5 is required for neuronal differentiation during development and acts as a tumor suppressor in various cancers." (PMID 26635563, 2015). "We also found that CHD5 expression was downregulated in HCC tissues compared with that in adjacent non-tumor tissues." (PMID 26287602, 2015). "Further supporting the role of CHD5 in cancer, the mouse Chd5 has been identified as a tumor suppressor." (PMID 24454811, 2014). "Chromodomain helicase DNA binding protein 5 (CHD5) was previously proposed to function as a potent tumor suppressor by acting as a master regulator of a tumor-suppressive network." (PMID 24454811, 2014). "Introduction of recombinant CHD5 into these cells inhibits proliferation, clonogenicity and tumour formation in xenograft assays." (PMID 24849318, 2014). "The data obtained from this study contribute to our understanding of the mechanisms regulating CHD5 gene expression in hematopoietic tumorigenesis, and facilitate optimization of anti-tumor therapy focused on repression of CHD5 expression." (PMID 24454811, 2014). "We confirmed our results at several different levels, including cell culture, tumor xenografts, and protein changes in CHD5-related pathways." (PMID 22235338, 2012).
tumor (continued). "The chromodomain helicase DNA binding protein 5 (CHD5) has recently been identified as a tumor suppressor in a mouse model." (PMID 22569290, 2012). "Chromodomain-helicase-DNA-binding protein 5 (CHD5) is a newly identified tumor suppressor that is frequently downregulated in a variety of human cancers." (PMID 22235338, 2012). "Enforced expression of miR-211 promotes tumor cell growth at least in part by downregulating the expression level of the CHD5 tumor suppressor." (PMID 22235338, 2012). "CHD5 was confirmed as the tumor suppressor in this region, as depletion of CHD5 phenocopied the proliferative defects found with deletions engineered in mice." (PMID 21931736, 2011). "Only one stage 4 tumor was found to be clearly immunoreactive for CHD5; at the time of analysis the patient is alive, 29 months from diagnosis." (PMID 20950435, 2010). "Recent findings have identified the CHD5 gene as a candidate tumor suppressor mapping to the smallest region of deletion (SRD) described in NB, 1p36.31." (PMID 20950435, 2010). "Intense CHD5 immunopositivity, equivalent to the primary tumor, was observed in >75% neuroblasts disseminated in the liver." (PMID 20950435, 2010). "Evidence supporting CHD5 as a tumor suppressor is the recently reported strong promoter methylation and transcriptional silencing of the remaining allele in 1p deleted NB cell lines." (PMID 20950435, 2010). "In stage 4s NB, CHD5 negative neuroblast bone marrow metastasis imply the existence of intratumoral clones with CHD5 differential expression in an otherwise histologically homogeneous tumor subtype." (PMID 20950435, 2010). "Recently, CHD5 was identified as a candidate tumor suppressor gene by the use of Cre-loxP site-specific recombinant technology to generate a region of gain or loss of mouse chromosome 4 corresponding to the human 1p36 locus." (PMID 18803848, 2008). "The results from functional experiments indicated that CHD5 could suppress tumor behaviors, and upon knockdown of CHD5, the tumor suppressive effects of LINC00862 and RBM47 were significantly diminished." (PMID 41487470, 2026). "Furthermore, CHD5 has been identified as a tumor suppressor that exerts inhibitory roles across a range of cancer types." (PMID 41487470, 2026). "Whole exome sequencing results revealed that such EV-DNA carried tumor-specific genetic mutations, including those occurring on known oncogenes and tumor suppressor genes in neuroblastoma (ALK, CHD5, SHANK2, PHOX2B, TERT, FGFR1, and BRAF), and represented the entire exome." (PMID 39402599, 2024). "Therefore, it is necessary to further explore the function of CHD5 in apoptosis, proliferation and tumor migration using various cell biology experimental approaches in the future." (PMID 35955624, 2022). "The results from our pan-cancer analysis revealed CHD5 was a tumor suppressor in multiple cancer types, and low expression of CHD5 may reduce the survival time of cancer patients." (PMID 35955624, 2022). "Although CHD5 is a tumor suppressor gene frequently altered in many human cancers, patients with CHD5 mutations do not develop tumors, suggesting that germline CHD5 alterations do not increase cancer risk." (PMID 36032672, 2022). "In vitro experiments validated that CHD5 has a tumor-suppressive function in NB cells." (PMID 34789839, 2022).
tumor (continued). "CHD5 has previously been reported to be a potential tumor suppressor gene in various solid tumors." (PMID 35955624, 2022). "Finally, we obtained six immune cell infiltration types from 8590 tumor samples across 38 tumor types, and showed that CHD5 gene expression was significantly correlated with immune infiltration in 28 types of cancers." (PMID 35955624, 2022). "Forced CHD5 expression decreased tumor incidence and moderately prolonged tumor latency." (PMID 34789839, 2022). "The Cancer Genome Atlas (TCGA), Genotype Tissue Expression (GTEx), and Cancer Cell Lines Encyclopedia (CCLE) datasets were utilized to determine the role of CHD5 in 33 types of cancers, including the expression level, prognosis, tumor progression, and immune microenvironment." (PMID 35955624, 2022). "CHD5 binds to unmodified N-terminus of histone 3 for tumor suppression." (PMID 33062682, 2020). "Initially, CHD5 expression was assessed in primary tumor tissue and in tissue array." (PMID 33062682, 2020). "Resent studies also showed that CHD5 acted as a tumor suppressor in HCC." (PMID 29568352, 2018). "CHD5 is a conventional tumour-suppressing gene in many tumours." (PMID 29907144, 2018). "The hypothesis that CHD5 works as a tumor-suppressing gene in HCC might simplify the tanglesome landscape of a chromatin remodeler." (PMID 29568352, 2018). "PHD-mediated histone 3 binding is required for CHD5-mediated tumor suppression." (PMID 28055972, 2017). "Our present study emphasizes the contribution of epigenetic regulation to RCC carcinogenesis and silencing of CHD5 could be a potential tumor biomarker for RCC diagnosis." (PMID 26943038, 2016). "Consequently, tumor suppressor genes located in this region, such as CHD5, are either lost or inactivated in these cancers." (PMID 26517514, 2015). "CHD5 was recently found to be a potential tumor suppressor gene in cancer." (PMID 26517514, 2015). "Thus, there is growing evidence that CHD5 has an important role in the regulation of neuronal differentiation, as well as in tumor suppression." (PMID 26245651, 2015). "Chromodomain helicase DNA binding protein 5 (CHD5) acts as a tumor suppressor in many cancers." (PMID 26517514, 2015). "Furthermore, Kaplan-Meier analyses revealed that underexpression of CHD5 significantly correlates with reduced overall survival and tumor-free survival rates (P = 0.002 and P = 0.031, respectively)." (PMID 26517514, 2015). "The ability of CHD5 to bind unmodified histone 3 (H3) is essential for tumor suppression." (PMID 24454811, 2014). "Our study shows that CHD5 is a NuRD-associated transcriptional repressor and identifies WEE1 as one of the CHD5-regulated genes that may link CHD5 to tumor suppression." (PMID 25247294, 2014). "In addition, ectopic expression of CHD5 suppressed cell proliferation and tumor growth of the MDA-MB-231 cell line by arresting cell cycle at the G0/G1 phase, and inhibited invasiveness of MDA-MB-231 and Hs 578T cells in vitro." (PMID 22569290, 2012). "miR-211 is significantly upregulated in other types of cancer and may function as an oncogene, which is consistent with the tumor suppressor function of CHD5." (PMID 22235338, 2012). "High CHD5 staining values were found to be significantly associated with INSS stages 1, 2, 3 (MYCN non-amplified) and 4s NB (n = 63), age at diagnosis <12 m (n = 63) and favorable tumor histology (n = 63); P < 0.001 for all the tested variables." (PMID 20950435, 2010). "First, the effects of CHD5 on tumor suppression and metastasis suppression may overlap." (PMID 34789839, 2022).
tumor (continued). "In addition, CHD5 inhibits clonogenic growth in vitro as well as tumor xenograft growth, suggesting that its inactivation may be involved in cancer development." (PMID 29682202, 2018). "Therefore, both PHDs and HELIC are required for the tumor suppressive function of CHD5." (PMID 26943038, 2016). "Subsequent PMA detected a deletion of both the CHD5 and p73 genes, which lie distal to DEAR1 in Chromosome 1p, suggestive of a terminal deletion of one allele with a breakpoint within the DEAR1 promoter, which then resulted in LOH encompassing two distal candidate tumor suppressors on Chromosome 1p." (PMID 19536326, 2009). "It was reported that EZH2 directly bound to the promoter site of CHD5 and promoted trimethylation of H3K27, resulting in down-regulation of CHD5 and promoting tumor growth in HCC." (PMID 37268997, 2023). "At least five genes located at 1p36 (CHD5, CAMTA1, KIF1B, CASZ1, and MIR34A) were already suggested to be tumor suppressors." (PMID 34956867, 2021). "To understand the role of CHD5 in RCC, we first measured the mRNA and protein levels in 24 paired tumor and adjacent tissues." (PMID 33062682, 2020). "Concomitantly α2β1 down regulated the expression of two other tumor suppressors, namely PKP1 (plakophilin 1) and CDH5 (chromodomain helicase DNA binding protein 5)." (PMID 30197754, 2018). "CHD5 expression can suppress the growth of many types of cancers, which suggests it is an important TSG in many forms of neoplasia." (PMID 26245651, 2015). "At least four genes (CD109, CHD5, LGR6, and ICAM5) displayed a different level of methylation, depending on the tumor location." (PMID 19750230, 2009). "While the novel 1p variants were predicted to be deleterious in silico, functional validation indicated that they did not consistently impair the effect of tumor suppressors KIF1Bβ and CHD5." (PMID 35768791, 2022). "CHD5 is a component of the CHD chromatin remodeling subfamily and is a tumor suppressor." (PMID 31769422, 2019). "Bone marrow aspirate smears of this patient exhibited widespread tumor dissemination with CHD5 negative neuroblast aggregates (data not shown)." (PMID 20950435, 2010). "CHD5, as a component of the NURD complex, also works in parallel with other NURD complex components containing histone deacetylase activity, which may further explain its role in tumor suppression." (PMID 41278204, 2025). "The obvious limitation of this approach is that the impact of CHD5 on the early steps of metastasis, dissociation of cells from the primary tumor and extravasation, could not be assessed in vivo." (PMID 34789839, 2022). "Importantly, CHD5 acts as a metastasis inhibitor in NB cells, independent of its tumor suppressor function." (PMID 34789839, 2022). "Thus, our study revealed that CHD5 is a novel direct target of EZH2, and may be part of a tumor suppressor network that is suppressed by EZH2." (PMID 26517514, 2015). "Previous studies have identified CHD5 and KIF1B as candidate tumor suppressor genes in this region, and more recently it was reported that disruption of PER3 function may indicate the likelihood of tumor recurrence in patients with ERα-positive tumors." (PMID 25106495, 2014). "Also we did not possess a source of mRNA to study CHD5 expression in tumor or compare melanocyte expression of CHD5 between affected individuals and controls." (PMID 18803848, 2008).
cancer (39 papers, 2007 to 2026). A tumor composed of atypical neoplastic, often pleomorphic cells that invade other tissues. "In NB, as in many adult cancers with 1p loss, one CHD5 allele is deleted while the second allele is transcriptionally silenced." (PMID 34789839, 2022). "To further explore the mutational landscape of CHD5 in different cancers, we analyzed the data from 30 cancers in the TCGA database." (PMID 35955624, 2022). "We observed frequent occurrence of synchronous mutations in patients with 1p gene variants, a phenomenon that has been observed in other cancers associated with mutations of CHD5." (PMID 35768791, 2022). "Currently, the CNV, TMB and MSI of CHD5 are less reported in these cancers, and our study provides new insights into the mutational landscape in these cancers." (PMID 35955624, 2022). "The first CHD gene linked with human cancer was CHD5, with the discovery that its locus 1p36.31 is often deleted in glioma and other tumors." (PMID 36430148, 2022). "Reduced CHD5 expression is associated with unfavorable clinical features and outcome of cancer patients." (PMID 26943038, 2016). "CHD5 binds and regulates an extensive number of cancer-associated loci, including tumorigenic Cdkn2a, and other genes encoding proteins implicated in chromatin dynamics and cancer-associated pathways." (PMID 24454811, 2014). "Subsequently, CHD5 has been reported to be mutated, deleted or silenced in a variety of human cancers including glioma, leukemia/lymphoma, melanoma, breast, prostate, ovarian and gastric cancers." (PMID 21931736, 2011). "Moreover, we observed that CHD5 expression was significantly associated with immune infiltration in 28 types of cancers." (PMID 35955624, 2022). "We mapped the mutational profiles of CHD5 across 30 types of cancers." (PMID 35955624, 2022). "Therefore, in our pan-cancer analysis, we evaluated the association between CHD5 expression and the TME." (PMID 35955624, 2022). "CHD5 is reported to be rarely mutated, but with frequent allelic loss in cancers." (PMID 26943038, 2016). "The CHD5 hypermethylation may implicate chromatin dynamics and cancer-associated pathways." (PMID 29568352, 2018). "Of note, similar to GNB1 both CDC42 and CHD5 were found to be highly methylated (methylated read count >700) in the BOCA-FR cancer cohort." (PMID 41345172, 2025). "This study aimed to systematically determine the expression pattern, prognostic value and potential function of CHD5 in different types of cancers." (PMID 35955624, 2022). "We further found that CHD5 expression was positively correlated with MSI in 5 types of cancers, including LUSC, LUAD, ACC, LGG, and CESC, but not negatively correlated with MSI in other types of cancers." (PMID 35955624, 2022). "The findings showed that in most cancer types (41/44), the level of immune cell infiltration was significantly positively correlated with the expression of CHD5." (PMID 35955624, 2022). "Eventually, seven ATPCR encoding genes, including ATRX, CHD5, CHD7, SMARCA4, SMARCA2, EP400, and ACTB, were identified as driver genes by at least two algorithms in certain cancer types." (PMID 35789070, 2022). "Nonetheless, few systematic studies have evaluated the roles of CHD5 through pan-cancer analysis using bioinformatics approaches." (PMID 35955624, 2022). "The findings showed that in most cancer types, the level of immune cell infiltration was significantly correlated with the expression of CHD5." (PMID 35955624, 2022). "Overall, our results showed that CHD5 expression was significantly downregulated in 25 types of cancers relative to the normal tissue and its expression levels were associated with neurological tumors." (PMID 35955624, 2022). "It was further found that CHD5 was downregulated in most cancer cells, with higher expression mainly in SCLC-21H (lung), U-2 OS (bone) and T-47d (breast) cancer cell lines." (PMID 35955624, 2022).